CXCR2 (C-X-C motif chemokine receptor 2)
Diseases named in the same sentence as CXCR2 in open-access papers (continued):
Sharing a sentence is not in itself a finding about the gene and the disease.
liver cysts (1 paper, 2024). "In conclusion even with decreased VCM concentrations in PVC manufacturing factories liver abnormalities that contained fatty liver, liver calcification, and liver cysts could still occur due to oxidative stress injury with involvement of IL-8 and CXCR2." (PMID 39108287, 2024).
Lupus (1 paper, 2022). "In particular, Cluster #42 for cv-score of 0.7 is a subpopulation of mature neutrophils (defined as CD66ace+CD66b+) whose levels of expression for CXCR1, CD15, CXCR2, IgA, CD66ace, CD66b, CD10, CD45RO, CD24 and CD16 best distinguishes between Lupus patients and Healthy donors." (PMID 36191000, 2022).
medullary carcinomas of the thyroid (1 paper, 2022). "In addition, high expression of CXCR2 has also been observed in PAs, medullary carcinomas of the thyroid, and pheochromocytomas." (PMID 35963638, 2022).
Mm (1 paper, 2014). "Despite this, blocking Il8/Cxcr2 signaling both pharmacologically and genetically caused no change in the nitrosative response by neutrophils to Mm infection indicating that the Il-8/Cxcr2 axis is not responsible for the increase in uninfected neutrophil nitrotyrosine." (PMID 24967596, 2014).
mucositis (1 paper, 2018). Mucositis is inflammation and damage of the mucous membranes lining the mouth and other parts of the gastrointestinal (GI) tract. "Here, overexpression of the chemokine receptor CXCR2 on MSCs improved cell migration to the inflamed mucosa and promoted cell survival in oral radiation/chemical-induced mucositis (RIM/CIM)." (PMID 29445104, 2018). "A transcription quantitative real-time PCR (RT-qPCR) analysis demonstrated that cultured MSCs at passage six expressed very low levels of chemokine receptors, including CXCR2, which is the receptor of the chemokine that is highly expressed in mucositis, CXCL2." (PMID 29445104, 2018). "Thus, we explored the potential therapeutic benefits of the transplantation of CXCR2-overexpressing MSCs (MSCsCXCR2) for mucositis treatment." (PMID 29445104, 2018).
neuroendocrine carcinoma (1 paper, 2016). A malignant neuroendocrine neoplasm composed of cells containing secretory granules that stain positive for NSE and chromogranin. "We found expression of IL-8 and its receptor CXCR2 in BON1 cells and in the human neuroendocrine carcinoma QGP1 cell line." (PMID 27506944, 2016).
Opportunistic infection (1 paper, 2018). An infection that is caused by a pathogen that would generally not be able to cause an infection in a host with a normal immune system. "Genetic variation in CXCR2, a receptor for IL-8, has not been significantly associated with HIV-1 VL or CD4 count, although the CXCR2 (+1208) T/C polymorphism is linked to the incidence of opportunistic infections among HIV patients in South Africa." (PMID 30534128, 2018).
papilloma (1 paper, 2024). A benign epithelial neoplasm that projects above the surrounding epithelial surface and consists of villous or arborescent outgrowths of fibrovascular stroma. "Papilloma induced by topical treatment of susceptible mice with 7, 12-dimethylbenz[α]anthracene (DMBA) and 12-O-tetradecanoyl phorbol-13-acetate (TPA) contained substantial numbers of MPO+ CXCR2+ Gr1+ MDSCs, and CXCR2 KO mice were profoundly resistant to the tumor induction." (PMID 38786066, 2024).
paroxysmal nocturnal haemoglobinuria (1 paper, 2018). "In addition to the current study, increased CXCR2 in leukocytes has been reported in obstructive coronary artery disease and paroxysmal nocturnal haemoglobinuria, but the mechanism(s) responsible for this increase have not been identified." (PMID 30540818, 2018).
penile cancer (1 paper, 2021). A primary or metastatic malignant neoplasm that affects the penis. "Experimental therapeutics on CXCL5/CXCR2 inhibitors would be the priority of future studies in penile cancer." (PMID 33458757, 2021).
plague (1 paper, 2021). Plague is a severe bacterial infection caused by the gram-negative bacterium Yersinia pestis. "The CXC chemokines are also produced in response to apoptosis or host cell damage, by signaling predominantly through CXC receptor 2 (CXCR2) and resulting in infiltration of PMNs to injured tissue to clean up dead cells, such as that which occurs in the necrotic bronchopneumonia of plague." (PMID 33669472, 2021).
pleural tumor (1 paper, 2018). "Our experiments using CXCR1- and CXCR2-deficient mice support that pleural tumor cell-secreted CXCL1/PPBP is cardinal for MPE and are in line with a previous study demonstrating increased production of CXCL1 by tumor cells during human MPE development that mobilizes regulatory T cells." (PMID 29445180, 2018).
pneumococcal meningitis (1 paper, 2017). An acute purulent infection of the meninges and subarachnoid space caused by Streptococcus pneumoniae, most prevalent in children and adults over the age of 60. "Treatment with a CXCR2 antagonist could also prevent mice mortality in a murine model of pneumococcal meningitis." (PMID 29326698, 2017).
Prostatic intraepithelial neoplasia (1 paper, 2023). "Prostatic intraepithelial neoplasia (PIN) is characterized by inflammation and is associated with an increase in CXCR2 expression compared to healthy tissue as well as an increase in CCL2/MCP-1 levels, which causes the recruitment of macrophages." (PMID 37108425, 2023).
pulmonary arterial hypertension (1 paper, 2025). Pulmonary arterial hypertension (PAH) is a group of diseases characterized by mean pulmonary artery pressure >20 mmHg and elevated pulmonary arterial resistance leading to right heart failure. "In contrast, endothelial cells largely express several other chemokine receptors including CCR4, CCR5, CCR6, CXCR2, CXCR4, and CXCR5, and CXCR4, which plays a key role in pulmonary arterial hypertension (PAH) through an autocrine signaling mechanism." (PMID 40859641, 2025).
retinal diseases (1 paper, 2020). "Pharmacological inhibition of CXCR2 suppresses EMT in RPE cells and could be a potential treatment for EMT-associated abnormal fibrosis in retinal diseases including PDR with tractional RD and PVR." (PMID 32132577, 2020).
rosacea (1 paper, 2025). A chronic erythematous skin disorder that affects the face. "This aligns with evidence that IL-17A-neutralizing antibodies suppress CXCL5/CXCR2 axis activation in murine rosacea models, attenuating both inflammatory and fibrotic responses." (PMID 40474977, 2025).
sarcopenia (1 paper, 2025). Progressive decline in muscle mass due to aging which results in decreased functional capacity of muscles. "In conclusion, the interplay between NETosis, along with its associated chemokine receptors CXCR1 and CXCR2, and sarcopenia encompasses intricate interactions among inflammatory pathways, cellular migration, and tissue remodeling." (PMID 40625358, 2025). "The genes identified in this study, namely CXCR1, CXCR2, and LPL, exhibit substantial potential as clinical diagnostic and therapeutic targets for sarcopenia." (PMID 40625358, 2025). "Univariate logistic regression showed that higher CXCR2 and CXCR1 expression increased sarcopenia risk, while lower LPL and IL18 expression was protective." (PMID 40625358, 2025). "Our research found that CXCR1 and CXCR2 were notably higher in the sarcopenia group, with single-gene GSEA and GSVA confirming their strong association with increased JAK-STAT pathway activity." (PMID 40625358, 2025). "The research pinpointed three genes associated with chemokines and NETosis (CXCR1, CXCR2, LPL) and developed highly accurate diagnostic models, offering a new and preliminary approach to differentiate sarcopenia and its early stages." (PMID 40625358, 2025). "By employing integrative bioinformatics strategies and multiple machine learning algorithms, we have successfully identified three signature chemokine- and NETosis-associated genes (CXCR1, CXCR2, and LPL) and constructed robust diagnostic models for sarcopenia detection." (PMID 40625358, 2025). "Exploring CXCR1 and CXCR2 expression on muscle cells and their role in muscle inflammation could clarify mechanisms behind sarcopenia." (PMID 40625358, 2025). "CXCR1 and CXCR2 levels were significantly higher, and LPL levels were lower in the sarcopenia group, consistent with the training group." (PMID 40625358, 2025). "Subsequently, an intersection of these three primary gene sets, as determined by univariate logistic regression, LASSO, and SVM-RFE models, led to the identification of three optimal signature genes—CXCR2, CXCR1, and LPL—for sarcopenia." (PMID 40625358, 2025). "To explore the roles of CXCR2, CXCR1, and LPL in sarcopenia-related pathways, we analyzed these genes individually using single-gene GSEA and GSVA." (PMID 40625358, 2025). "High CXCR1 and CXCR2 and low LPL levels may indicate sarcopenia progression, aiding early detection." (PMID 40625358, 2025).
schistosomiasis (1 paper, 2023). An infectious disease caused by parasitic trematodes of the genus Schistosoma that colonize human blood vessels and release eggs that can cause granulomatous reactions leading to acute (swimmer's itch or acute schistosomiasis syndrome) or chronic disease. "A preliminary study showed that NKT cells were increased in patients with schistosomiasis and that CXCR2 + NKT cells were proinflammatory cells." (PMID 37817226, 2023). "This preliminary study suggests that the increased presence of CCR2 + monocyte and CXCR2 + NKT cells might participate in the progression of schistosomiasis." (PMID 37817226, 2023). "In conclusion, our results provide further understanding of the pathogenesis of human schistosomiasis, and the role of CCR2+ monocytes and CXCR2+ NKT cells in schistosomiasis requires further study." (PMID 37817226, 2023).
sickle cell disease (1 paper, 2025). Sickle cell anemias are chronic hemolytic diseases that may induce three types of acute accidents: severe anemia, severe bacterial infections, and ischemic vasoocclusive accidents (VOA) caused by sickle-shaped red blood cells obstructing small blood vessels and capillaries. "Because G-CSF/AMD3100 mobilization is problematic, specifically in patients with sickle cell disease, we used G-CSF-free mobilization regimens, the CXCR2-inhibitor tGroβ together with AMD3100 or AMD3100-tGroβ together with the VLA4 inhibitor WU-106." (PMID 40231246, 2025).
skin aging (1 paper, 2023). The gradual irreversible changes in structure of skin that occur as a result of the passage of time.. "Then, we confirmed the down-regulated expressions of ABCC4, PTGER3, BCEH, HPGD, and MOXD1 in normal group, while AR, CXCR2, HSD17B2, ODC1, PI3, PLAU and THBS2 were up-regulated in skin aging group." (PMID 37310405, 2023). "In addition, ROC curve verified that these hub-target had certain sensitivity and specificity for the diagnosis of skin aging (AUC greater than 0.5), AR, BCEH, CXCR2, HPGD and PI3 performed well especially." (PMID 37310405, 2023).
small cell carcinoma (1 paper, 2015). A neuroendocrine carcinoma composed of small malignant cells which are often said to resemble "oat cells" under the microscope. "This study focused on the impact of CXCR1 and CXCR2 antagonism by G31P on proliferation, migration, survival and growth of non-small cell carcinoma cells and tumors in vitro and in vivo, the latter as determined in a xenograft mouse model." (PMID 26087179, 2015).
staphylococcal infection (1 paper, 2018). An infection caused by Staphylococcus. "Direct activation of TLRs in neutrophils, specifically TLR2 in staphylococcal infections, downregulates the expression of chemokine receptor CXCR2 that keeps their recruitment to infectious foci." (PMID 29867945, 2018).
staphylococcus aureus infection (1 paper, 2025). An infectious process in which the bacteria Staphylococcus aureus is present. "Specifically, in staphylococcus aureus infections, the LukED toxin enhances neutrophil destruction and NET formation by targeting CXCR1 and CXCR2, thus intensifying the infection’s severity." (PMID 40625358, 2025).
steatosis (1 paper, 2013). Increased lipid within the cytoplasm of cells. "IL8RB/CXCR2 is a notable exclusion with its overexpression correlating with steatosis and diagnosis of NASH as well as fibrosis." (PMID 23661906, 2013).
streptococcal infection (1 paper, 2022). Any of the several infectious disorders caused by members of streptococcus, a genus of gram positive bacteria belonging to the family Streptococcaceae. "Potential SpyCEP antagonists modelled on CXCL8 but with reduced CXCR1 and CXCR2 activity have previously been described and could in theory provide adjuvant therapies for more severe invasive streptococcal infections that fail to respond to antibacterial agents alone." (PMID 34649250, 2022).
temporal lobe epilepsy (1 paper, 2024). A localization-related (focal) form of epilepsy characterized by recurrent seizures that arise from foci within the temporal lobe, most commonly from its mesial aspect. "The CXCR2 receptor showed increased expression in temporal lobe epilepsy (TLE) patients, and using a CXCR2‐selective antagonist could inhibit its upregulation." (PMID 38361811, 2024).
thyroid (1 paper, 2025). "Indeed, a significant down-regulation of CXCR2 mRNA expression was observed in both normal and cancer thyroid cells after treatment with AZD5069." (PMID 38900374, 2025).
tongue cancer (1 paper, 2014). A malignant neoplasm affecting the tongue. "The two ligands for CXCR1, CXCL6 and CXCL8, which also activate CXCR2, are both up-regulated, indicating that a shift towards activation of CXCR2 could be of importance for tongue carcinoma." (PMID 24395654, 2014).
tongue squamous cell carcinoma (1 paper, 2022). A squamous cell carcinoma that arises from the tongue. "A similar mechanism was demonstrated for tongue squamous cell carcinoma, where the downregulation of miR-940 expression increased CXCR2 expression and thus the response of these cancer cells to CXCR2 ligands." (PMID 35216283, 2022).
Tumorous Salivary Glands (1 paper, 2022). "In salivary gland tumors, there has been an increase in the expression of CD44s, CD44v6, CXCR2, and IL-1β." (PMID 35626430, 2022). "Collectively, both CD44s and CXCR2 could be biomarkers for salivary gland tumors and an increase in CD44s and CXCR2 expression might be associated with the aggressiveness of the malignancy of salivary gland tumors." (PMID 35626430, 2022). "The levels of IL-1β, CXCL1, and CXCR2 in salivary gland tumors were investigated in this study." (PMID 35626430, 2022). "Therefore, our findings suggest that CD44s, CD44v6, and CXCR2 might be involved in the release of IL-1β in salivary gland tumors, and IL-1β may play a crucial role in the promotion of the aggressiveness of salivary gland tumors." (PMID 35626430, 2022).
Ureteral obstruction (1 paper, 2022). Obstruction of the flow of urine through the ureter. "CXCR2 is one of most increased members among CXCR family in unilateral ureteral obstruction (UUO) mice." (PMID 35592244, 2022). "Administration of SB225002, a selective CXCR2 antagonist, significantly inhibited the activation of β-catenin signaling, restored mitochondrial function, protected against tubular cell senescence and renal fibrosis in unilateral ureteral obstruction (UUO) mice." (PMID 35592244, 2022).
visceral leishmaniasis (1 paper, 2011). A severe form of leishmaniasis characterized by irregular bouts of fever, substantial weight loss, swelling of the spleen and liver, and anemia (which may be serious). "Here we investigate the role of CXCR1/CXCR2 in visceral leishmaniasis (VL) in India." (PMID 22171941, 2011).
Zinc deficiency (1 paper, 2019). A deficiency of the essential metal Zinc; an essential cofactor for many enzymes. "Therefore, CXCR2, ANXA1, and CCR3 would be potential biomarkers for zinc deficiency in mice." (PMID 30770772, 2019). "In addition, therapeutic drug prediction indicated that CXCR2 and ANXA1 may be targets of drugs, suggesting these two genes may be implicated as therapeutic targets to reduce risk of zinc deficiency." (PMID 30770772, 2019).
tumor (1,204 papers, 2008 to 2026). "The combination of anti-PD-1 antibodies and MEK inhibitors induced recruitment of tumor-associated neutrophils (TANs) via CXCR2, an IL-8 receptor, and increased memory CD8+ T cells and IFN-γ production in treatment-sensitive tumors." (PMID 41855192, 2026). "P.g. and F.n. also stimulate tumor-associated neutrophils via CXCL2/CXCR2, accelerating tumor invasion." (PMID 40924302, 2025). "linked CD70 to immunosuppression and augmented anti-tumor responses by engineering IL-8 receptor (CXCR1/CXCR2)-modified anti-CD70 CAR-T, leveraging radiation-induced IL-8 release to enhance tumor trafficking." (PMID 40896423, 2025). "A significant difference in the response to anti‐PD‐1 therapy was observed between wild‐type and CXCR2‐deficient tumor‐bearing mice." (PMID 40452814, 2025). "Previous studies have shown that knockout of the mouse homolog of CXCR2 (Cxcr2) reduces infiltration of MDSCs, neutrophils, and tumor-associated macrophages into mouse PDAC tumors." (PMID 40427538, 2025). "Increased expression of TFCP2L1 as a result of blocking CXCR2 activity in mouse models of melanoma resulted in decreased expression of genes involved in tumor growth and increased expression of genes associated with tumor suppression." (PMID 40813991, 2025). "In ovarian cancer, CXCR2 is significantly associated with macrophage infiltration, particularly influencing both M1 and M2 macrophages in the tumor microenvironment." (PMID 40330466, 2025). "The IL-8/CXCR2 axis is frequently upregulated across multiple malignancies and is associated with poor prognosis and increased tumour aggressiveness." (PMID 41163221, 2025). "PD‐1 blockade was ineffective in wild‐type tumor‐bearing mice, whereas a significant reduction in tumor growth was observed in CXCR2‐deficient mice." (PMID 40452814, 2025). "Temozolomide (TMZ), a common alkylating agent used in adjuvant chemotherapy for HGG, has been shown to upregulate the CXCL8-dependent CXCL2/CXCR2 axis, promoting angiogenesis and the recruitment of tumor-associated macrophages." (PMID 41432874, 2025). "Heightened levels of CXCL8 along with overexpression of CXCR1 or CXCR2 have been implicated in promoting tumor cell proliferation and metastasis through the activation of PI3K/AKT and ERK1/2 MAPK signaling pathways." (PMID 40124384, 2025). "CXCR2 signaling enhances the invasive capacity of NB cells co-cultured with tumor-associated macrophages, and single-cell transcriptomics revealed that the upregulation of CXCR2 expression promoted NB cell proliferation via myeloid-derived suppressor cells." (PMID 41155662, 2025). "We analyzed publicly available single-cell data from HNSCC patients (GSE234933) to validate which cell types are specifically associated with the IL-8 receptors CXCR1 and CXCR2 in the tumor microenvironment of HNSCC patients." (PMID 39905539, 2025). "While P. gingivalis was able to promote oral cancer progression in C57BL/6 mice, which was associated with its ability to recruit tumor-associated neutrophils (TANs) through the activation of the CXCL2/CXCR2 signaling in the tumor microenvironment." (PMID 40361452, 2025). "Increasing CXCR2 expression on these cells causes tumor infiltration by these cells, giving an anti-tumor effect, as shown in experiments in vitro on renal cell carcinoma." (PMID 40427171, 2025). "Pharmacologic and genetic perturbations across gastrointestinal and colitis-associated models demonstrate that CXCR2 signaling governs granulocytic recruitment and tumor promotion, providing mechanistic support for therapeutic targeting of this pathway." (PMID 41567197, 2025). "CRC harbors a reproducible landscape of suppressive myeloid states anchored by SPP1high tumor-associated macrophages, CXCR2-driven granulocytic programs, and mregDC modules." (PMID 41567197, 2025). "CXCL1 and its receptor CXCR2 are overexpressed and linked to tumor progression, highlighting their diagnostic and therapeutic potential." (PMID 40943634, 2025).